USP1 (ubiquitin specific peptidase 1)
Diseases named in the same sentence as USP1 in open-access papers (continued):
Sharing a sentence is not in itself a finding about the gene and the disease.
breast carcinoma (27 papers, 2020 to 2026). "The mechanistic experiments revealed that USP1 associated with ERα and increased ERα stability via prohibiting ERα K48-linked poly-ubiquitination in breast cancer cells." (PMID 33123289, 2020). "Our study showed that USP1 stabilized ERα via inhibiting K48-linked poly-ubiquitination of ERα, which provided a novel insight of DUBs in modulating hormone signaling and breast cancer progression." (PMID 33123289, 2020). "In our current study, we reported USP1 associated with ERα, inhibited ERα poly-ubiquitination and degradation in breast cancer cells, which indicated that USP1 linked to breast cancer proliferation and invasion via estrogen signaling." (PMID 33123289, 2020). "Given that TAZ, an OS oncogene about 55 kDa, was reported to form a complex with USP1 to affect the metastatic properties of breast cancer 21, we speculated whether this association exists in OS and confers to the regulatory effects of USP1." (PMID 35637948, 2022). "Since USP1 could associate with ERα in breast cancer cells, we further investigate the biological effect of such interaction." (PMID 33123289, 2020). "In breast cancer, hyperactivation of the deubiquitinase USP1 promotes metastasis of breast cancer cells to lung, upregulates the expressions of many pro-metastatic genes in cancer cells, and enhances cell migration and invasion in vitro." (PMID 40894221, 2025). "Research has demonstrated that USP1 stabilizes estrogen receptors in breast cancer, thereby promoting tumor growth and inhibiting differentiation in osteosarcoma." (PMID 40136409, 2025). "For instance, USP1 stabilized estrogen receptor alpha (ERα) to promote proliferation and invasion of breast cancer cells." (PMID 39044157, 2024). "As a well-known enzyme in this category, USP1 can promote proliferation, invasion, and metastasis of breast cancer and hepatocellular carcinoma through deubiquitination." (PMID 37821462, 2023). "USP1, a member of the deubiquitylation enzyme family, has been reported to be involved in several malignancies, such as breast cancer, B/T cell acute lymphoblastic leukemia and glioblastoma." (PMID 36352191, 2023). "Given that ML323, a selective inhibitor of USP1, presented the abilities to sensitize resistant OS cells to cisplatin 19 along with anti-metastatic effects in breast cancer." (PMID 35637948, 2022). "USP1 interacts with KPNA2, and deubiquitination of KPNA2 is a key factor in USP1 promoting metastasis; therefore, USP1 inhibition can markedly reduce the migration of breast cancer cells." (PMID 36357365, 2022). "Overexpression of USP1 increases the expression of several prometastatic genes in breast cancer cells, promote cell migration and invasion, thereby promoting metastasis of breast cancer cells." (PMID 35923700, 2022). "USP1 is reportedly overexpressed in some tumor tissues, including gastric cancer, breast cancer and lung cancer." (PMID 35637948, 2022). "In breast cancer, the upregulation of USP1 expression and deubiquitination of KPNA promotes cell proliferation, migration, and invasion in vitro and promotes lung metastasis of breast cancer cells." (PMID 36357365, 2022). "For example, in breast cancer, USP1 regulates the stability of the TAZ protein through ubiquitination modification, and inhibition of USP1 can reduce the proliferation and migration of breast cancer cells." (PMID 36357365, 2022). "According to TCGA and KMPLOT databases, high expression of USP1 is relevant to poor prognosis in ERα+ breast cancer patients." (PMID 34575114, 2021). "In conclusion, we identified an interesting deubiquitinase USP1 in facilitating ERα signaling in breast cancer cells." (PMID 33123289, 2020). "Ubiquitin specific protease 1 (USP1) was observed to play critical role in ERα signaling in breast cancer." (PMID 33123289, 2020). "To assess the novel regulators of TAZ at the protein level, we used an siRNA library screen of DUBs and identified that USP1 can alter TAZ stability in breast cancer cells." (PMID 33114077, 2020).
breast carcinoma (continued). "WST assay shows that USP1 depletion significantly decreases breast cancer cell proliferation in MCF-7 and T47D cells." (PMID 33123289, 2020). "We identify that USP1, which are elevated in human breast cancer samples and related to poor survival in ERα positive breast cancer patients." (PMID 33123289, 2020). "In order to investigate the impact of USP1 on breast cancer phenotypes, we deplete USP1 in breast cancer cells." (PMID 33123289, 2020). "The TCGA data showed that USP1 was elevated in human breast cancer compared with normal breast tissue." (PMID 33123289, 2020). "Conversely, loss of function of USP1 reduces TAZ protein levels through increased poly-ubiquitination, causing a decrease in cell proliferation and migration of breast cancer cells." (PMID 33114077, 2020). "While the roles of BIRC5 and E2F1 in drug resistance in HER2 breast cancer are understood, the involvement of USP1 and TRFC remains unclear." (PMID 38534787, 2024). "Additionally, evidence showed that USP1 functions as a deubiquitinase to regulate TAZ specifically in breast cancer." (PMID 35906484, 2023). "In addition, YAP/TAZ, a key effector of the Hippo signaling pathway, increases protein stability via USP1, resulting in increased proliferation and migration of breast cancer cells." (PMID 36153316, 2022). "In addition, as expected, USP1 expression positively correlates with KPNA2 in breast cancer tissues." (PMID 34575114, 2021). "USP1 enhances breast cancer metastasis by deubiquitinating and stabilizing KPNA2." (PMID 34575114, 2021). "Clinical evidence shows that USP1 expression is related to adverse outcomes in breast cancer." (PMID 34575114, 2021). "As a novel modulator of ERα signaling, disturbing USP1 activity or affecting USP1 expression could be a plausible way to treat luminal types of breast cancer." (PMID 33123289, 2020). "We further investigate the expression of USP1 in human breast cancer in public available datasets." (PMID 33123289, 2020). "The expression of USP1 is elevated in human breast cancer compared with normal mammary tissues." (PMID 33123289, 2020). "In conclusion, our data implicate a non-genomic mechanism by USP1 via stabilizing ERα protein controls ERα target gene expression linked to breast cancer progression." (PMID 33123289, 2020). "USP1 depletion inhibited breast cancer cell progression and ERα signaling activity." (PMID 33123289, 2020). "Besides, the expression of USP1 was correlated with poor survival in breast cancer." (PMID 33123289, 2020). "USP1 could promote breast cancer cell invasion and proliferation via stabilizing ERα protein." (PMID 33123289, 2020). "It is reported that USP1 targets ULK1 and regulates canonical autophagy in breast cancer, which is consistent with our result in PDAC cells." (PMID 39814232, 2025). "We observed significantly high expression patterns for both USP1 and MAST1 in lung cancer (n = 32), colon cancer (n = 32), and breast cancer (n = 21) samples." (PMID 35966591, 2022). "ML-323, an inhibitor of the USP1/UAF1 deubiquitinase complex, has been reported to have anti-tumor effects in numerous cancers including colorectal cancer and breast cancer." (PMID 36357365, 2022). "Recent reports have documented that TAZ can be directly deubiquitinated and stabilized by USP1, USP10, OTUB2 and JOSD2 in hepatocellular carcinoma, breast cancer and cholangiocarcinoma." (PMID 35931679, 2022). "More recently, USP1 has been found to deubiquitinate and stabilize KPNA2, leading to pro-metastatic functions in breast cancer." (PMID 33114077, 2020). "Knockdown of USP1 reduces TAZ protein levels through increased poly-ubiquitination, leading to a decrease of breast cancer cell proliferation and migration in vitro and reduced tumor formation in vivo." (PMID 33114077, 2020). "To understand the expression of USP1 and TAZ at the protein level, we analyzed a panel of breast cancer cell lines." (PMID 33114077, 2020).
breast carcinoma (continued). "For example, USP1 increases the expression of pro-metastatic genes, especially nuclear protein KPNA2, and USP1 deubiquitinates KPAN2 by interacting with KPAN2, thereby promoting the metastasis of breast cancer via stabilization of KPNA2." (PMID 36153316, 2022). "It is known that USP1 and TAZ both have oncogenic functions in breast cancer." (PMID 33114077, 2020). "To address whether USP1 and TAZ could be used as markers for the prognosis of breast cancer patients, we used gene set enrichment analysis (GSEA) and immunohistochemistry (IHC) staining of TNBC cases." (PMID 33114077, 2020). "Furthermore, we demonstrated a strong expression correlation between USP1 and TAZ in breast cancer patients." (PMID 33114077, 2020). "Moreover, we showed a strong positive correlation between USP1 and TAZ in breast cancer patients." (PMID 33114077, 2020). "Since USP1 has been shown to regulate other targets, such as: KPNA2, that drive breast cancer metastasis, targeting this enzyme may be beneficial in the treatment of breast cancer patients, more specifically, TNBCs." (PMID 33114077, 2020). "Since USP1-mediated deubiquitination of KPNA2 contributes to tumorigenesis, researchers have found that inhibitors of USP1 such as pimozide and ML323 decrease breast cancer metastasis without showing obvious cytotoxicity in mice, offering a novel therapeutic target to be explored in the future." (PMID 34575114, 2021).
hepatocellular carcinoma (17 papers, 2020 to 2026). A malignant tumor that arises from hepatocytes. "USP1 expression was elevated in human hepatocellular carcinoma and associated with poor survival in hepatocellular carcinoma patients." (PMID 37041150, 2023). "We revealed that USP1 expression was promoted in hepatocellular carcinoma and associated with poor survival." (PMID 37041150, 2023). "The CCK8 assay showed that USP1 depletion sharply inhibited hepatocellular carcinoma cell proliferation." (PMID 37041150, 2023). "We further examined the impact of USP1 on the hepatocellular carcinoma phenotype by depleting USP1 in HLF and Hep3B cells." (PMID 37041150, 2023). "In summary, according to all these data, USP1 plays a critical role in facilitating the progression of hepatocellular carcinomas." (PMID 37041150, 2023). "USP1 interacted with the TAZ protein and suppressed its K11-linked polyubiquitination in hepatocellular carcinoma cells." (PMID 37041150, 2023). "The CCK8 assay indicated that USP1 depletion significantly inhibited hepatocellular carcinoma cell growth, which was partially reversed by further TAZ overexpression, and these results were confirmed by the colony formation assays." (PMID 37041150, 2023). "As USP1 modulates Hippo signaling, modulating its activity or gene expression level is a promising strategy for the treatment of hepatocellular carcinoma." (PMID 37041150, 2023). "Our results showed that USP1 depletion significantly inhibited the protein level of Ki67 and N-cadherin in hepatocellular carcinoma cell." (PMID 37041150, 2023). "Ubiquitin‐specific protease 1 (USP1) is significantly overexpressed in hepatocellular carcinoma (HCC)." (PMID 32951278, 2020). "However, in B-cell lymphoma and hepatocellular carcinoma, USP1 inhibition greatly enhances autophagic activity." (PMID 39814232, 2025). "Based on these findings, we propose that pharmaceutically targeting USP1 function or inhibiting USP1 expression may be effective in suppressing Hippo/TAZ-driven hepatocellular carcinoma." (PMID 37041150, 2023). "We identified USP1 as an oncogene in hepatocellular carcinoma." (PMID 37041150, 2023). "We further investigated the expression of USP1 in hepatocellular carcinoma." (PMID 37041150, 2023). "Considering these results collectively, we propose that USP1 could be a positive regulator of the Hippo/TAZ axis in human hepatocellular carcinoma." (PMID 37041150, 2023). "To inquire whether TAZ is involved in USP1-mediated proliferation, migration, colony formation and apoptosis in hepatocellular carcinoma cells, we carried out several rescue experiments." (PMID 37041150, 2023). "Moreover, USP1 is reportedly a promising target for regulating the progression of hepatocellular carcinoma." (PMID 37041150, 2023). "Considering these results collectively, we speculate that USP1 could be a promising positive regulator of the Hippo signaling in human hepatocellular carcinoma." (PMID 37041150, 2023). "Furthermore, Transwell assay indicated that USP1 depletion significantly inhibited hepatocellular carcinoma cell migration capacity, which was partially reversed by further TAZ overexpression." (PMID 37041150, 2023). "A previous study found an interaction between RPS16 and USP1 in hepatoma cells." (PMID 35873150, 2022). "This study aimed to determine the role of USP1 as a therapeutic target in hepatocellular carcinoma (HCC)." (PMID 36357365, 2022). "In this study, we comprehensively analysed the role of ubiquitin‐specific protease 1(USP1) in hepatocellular carcinoma (HCC) using data from a set of public databases." (PMID 32951278, 2020). "We identified USP1 as a novel effector of TAZ stability and hepatocellular carcinoma progression." (PMID 37041150, 2023). "In addition, further analysis of USP1 and TAZ expression revealed a positive correlation between USP1 and TAZ protein expression in 62 samples of hepatocellular carcinoma collected from Qilu Hospital (p = 0.018)." (PMID 37041150, 2023).
hepatocellular carcinoma (continued). "In addition, we examined the localization of USP1 and TAZ in hepatocellular carcinoma cells." (PMID 37041150, 2023).
ovarian carcinoma (15 papers, 2015 to 2026). A malignant neoplasm originating from the surface ovarian epithelium. "But there were many studies showing the important roles of USP1 in the carcinogenicity of ovarian cancer." (PMID 41541703, 2026). "For example, Sonego's group demonstrated that inhibition of USP1 increased drug sensitivity and decreased metastatic dissemination in ovarian cancer cells through the control of Snail." (PMID 41541703, 2026). "The study showed that USP1 upregulation confers platinum resistance to ovarian cancer cell, and inhibiting USP1 reverses platinum resistance." (PMID 39814232, 2025). "USP1 contribution to the aggressive feature of ovarian cancer has been dissected out 80 and inhibitors of this DUB are being developed." (PMID 39430244, 2024). "Recently, the USP1 inhibitor ML323 was shown to inhibit the proliferation of ovarian cancer cells and exhibit anticancer activity against esophageal squamous cell carcinoma." (PMID 39513905, 2024). "A previous study has shown that inhibiting USP1 can reduce the viability of BRCA1/2 mutant cancer cells (e.g. ovarian cancer cells), thereby USP1 is a SL partner of BRCA1 and has been a promising drug target in clinical cancer therapy." (PMID 37387166, 2023). "USP1 also induces deubiquitination and stabilization of Snail, metastasis, and resistance to platinum in ovarian cancer." (PMID 36153316, 2022). "In summary, our work has identified the critical role of ML323/USP1 axis against anti-ovarian cancer." (PMID 35923700, 2022). "However, whether USP1 underlies ovarian cancer (OV) progression remains unclarified." (PMID 35923700, 2022). "In order to address the difference of USP1 between ovarian cancer and normal ovarian epithelial tissue, we analyzed ovarian cancer samples in TCGA and normal ovarian epithelial samples in GTEx, and plotted the box plots of expression (p < 0.001)." (PMID 35923700, 2022). "In order to perform functional analysis, the expression of USP1 was determined in ovary cancer cell lines." (PMID 35923700, 2022). "There was only a limited study to show the roles of USP1 in ovarian cancer." (PMID 41541703, 2026). "Additionally, high USP1 expression is correlated with the unfavorable prognosis of renal cell carcinoma, ovarian cancer, and liver cancer." (PMID 39735674, 2025). "Efforts have been made on pharmacological targeting of USP1 119-126 and they may pave the way to new opportunities for ovarian cancer treatment." (PMID 39430244, 2024). "According to the findings, ML323 could be a reliable anti-ovarian cancer agent though targeting USP1." (PMID 35923700, 2022). "USP1 was shown to be upregulated in ovary cancer cells and tissue samples." (PMID 35923700, 2022). "Similarly, knockdown of USP1 also inhibited the proliferation of ovarian cancer cells." (PMID 35923700, 2022). "Further, USP1 could be a prognostic marker and anti-cancer therapeutic target for ovarian cancer." (PMID 35923700, 2022). "USP1 dependency has been related to the aberrant processing of mono- and poly-Ub PCNA in BRCA1/2 mutant tumors as well as in BRCA1/2 wild-type cell lines including ovarian cancer cells." (PMID 39430244, 2024). "Recently, a USP1 inhibitor was adapted to sensitize human cisplatin-resistant NSCLC cells 19, and it also destabilizes Snail expression and increases platinum sensitivity in ovarian cancer." (PMID 35966591, 2022).
non-small cell lung carcinoma (13 papers, 2013 to 2025). A group of at least three distinct histological types of lung cancer, including non-small cell squamous cell carcinoma, adenocarcinoma, and large cell carcinoma. "Another significant member, USP1, is regulated at the translational level in cisplatin-resistant non-small cell lung cancer (NSCLC) cell lines." (PMID 38702734, 2024). "Regarding inhibitors of USPs, GW7647 and pimozide non-competitively inhibited USP1 with inhibition constants (Ki) of 0.7 and 0.5 μM, respectively; inhibiting cellular USP1 activity by these agents sensitized human cisplatin-resistant non-small cell lung cancer cells to cisplatin." (PMID 29039082, 2017). "This view has gained recent support with the finding that USP1 inhibition may contribute to revert cisplatin resistance in an in vitro model of non-small cell lung cancer (NSCLC)." (PMID 23937906, 2013). "Two small molecule USP1/UAF1 inhibitors, pimozide and GW7647, enhanced the cytotoxicity of cisplatin and decreased cell division in non-small cell lung cancer cell lines." (PMID 35198436, 2021). "A third USP1/UAF1 inhibitor, ML323, was found to increase the cytotoxic effect of cisplatin on osteosarcoma and non-small cell lung cancer cells." (PMID 35198436, 2021).
gastric cancer (12 papers, 2011 to 2025). A primary or metastatic malignant neoplasm involving the stomach. "We found that MAPKAPK5 and USP1 proteins were highly expressed in gastric cancer tissues, while the ZFP36 protein was lowly expressed in tumor tissues." (PMID 35719376, 2022). "Increasing evidences suggested that USP1 plays vital roles in tumor pathogenesis and development, and aberrant overexpression of USP1 has been found frequently in many cancers including gastric cancer, cervical cancer, melanoma, and so on." (PMID 41328326, 2025). "Finally, we measured the expression of USP1 on a gastric cancer “progression” TMA containing normal gastric epithelia, intestinal metaplasia, dysplasia, primary carcinomas and metastases." (PMID 21283576, 2011). "Analysis of USP1 expression in the progression of gastric cancer." (PMID 21283576, 2011). "A study involving 188 patients with gastric cancer (GC) revealed that the mRNA levels and protein levels of USP1 were overexpressed in GC tissue than in adjacent normal tissue, and further analysis indicated that USP1 may promote GC metastasis by upregulating ID2 expression." (PMID 36685967, 2022).